GBP2 (guanylate binding protein 2)
Diseases named in the same sentence as GBP2 in open-access papers (continued):
Sharing a sentence is not in itself a finding about the gene and the disease.
infection (continued). "Consistent with reduced IFNγ expression, the mRNA induction of Nos2, Gbp1, Gbp2, Gbp4, Gbp5, Ido1 and Acod1 was severely impaired in the spleens of Myd88−/− mice after intraperitoneal infection." (PMID 36479617, 2023). "Many pieces of evidence indicated that GBP2 is an important participant in the host’s defence against intracellular pathogen infection." (PMID 37592228, 2023). "According to the study, GBP2 overexpression suppresses ECTV replication in a dose-dependent manner, while GBP2 knockdown promotes ECTV infection." (PMID 37764102, 2023). "For instance, BECs expressed increased Gbp4 and Gbp2, and LECs expressed increased Gbp4, Gbp2, and Gbp7 upon infection." (PMID 35789215, 2022). "IFN-α/β and IFN-γ induce the production of GBP2, which also plays an important role in resistance to infection by intracellular pathogens." (PMID 36115937, 2022). "Expression of gbp2 returned to uninfected levels by day 28 post-infection in all tissues, which is a pattern that has been previously reported for ISGs in joints during murine Lyme arthritis." (PMID 33524035, 2021). "After STM infection migratory ILCs express significantly higher levels of Ccl3, Gbp2, Gbp6, Irf1, Irf4, Irf7, Pml and Stat1, all of which are regulated in response to interferon gamma." (PMID 33414524, 2021). "In contrast, the ISG gbp2 was elevated in all tissues tested including brain tissues at day 7 post-infection, again in agreement with the RNA-seq dataset." (PMID 33524035, 2021). "GBP2 and ZBP1 expression are also increased at 14dpi compared to naïve controls, but while GBP2 remains constant until the late stage of infection, ZBP2 is significantly increased at each time point (right)." (PMID 33816350, 2021). "Loss of either GBP2 or GBP5 alone was sufficient to render bone marrow-derived macrophages (BMDMs) and mice highly susceptible to infection by B. thailandensis." (PMID 32150572, 2020). "We also found that compared with wild-type BMDMs, BMDMs from Irgb6-deficient mice displayed impaired T. gondii killing activity, increased infection rate, and reduced recruitment of Irgb10, Irga6, Gbp1, Gbp2, Gbp1-5, ubiquitin, and p62." (PMID 31852733, 2020). "The diversification of GBP pathogen-targeting capabilities is also highly relevant to animal models of infection as the mouse ortholog of hGBP1, mouse GBP2, detects cytosolic S. flexneri through a poorly defined process independently of a bona-fide PBM." (PMID 32430466, 2020). "Lastly, we also observed notably lower PAMP- or infection-induced expression of Gbp2 in 129/Sv compared to C57BL/6 mice." (PMID 31544161, 2019). "flexneri infections lead to high expression of Gbp2b mRNA and protein, but relatively low expression of Gbp2 in 129/Sv compared to C57BL/6J mice." (PMID 31544161, 2019). "To test that, we transfected BMDMs primed with PAM3CSK from C57BL/6, Gbp2-/- and Gbpchr3-/- mice with B. abortus LPS using FuGENEHD and evaluated propidium iodide uptake in real time during 8 h of infection." (PMID 30589883, 2018). "We identified and confirmed that Gbp1 and Gbp2 are ubiquitinated in WT MEFs in a Toxoplasma-infection independent fashion." (PMID 29510761, 2018). "Nevertheless, we identified and confirmed Gbp1 and Gbp2 as being ubiquitinated in a Toxoplasma-infection independent manner." (PMID 29510761, 2018). "Analysis of global gene expression of bone marrow derived macrophages from BALB/c mouse demonstrated upregulation of expression of Gbp2b/Gbp1, Gbp2, Gbp3, Gbp6, and Gbp7 after 24 hours of infection with Leishmania major promastigotes." (PMID 29467757, 2018). "In accordance, we observed here anup-regulated expression of Irgm1, Igtp and Gbp2 in the adiposetissue early upon infection." (PMID 27001522, 2016). "Notably, T. gondii has evolved countermeasures: the rhoptry effector protein 54 promotes infection by modulating GBP2 loading onto parasitophorous vacuoles." (PMID 41181145, 2025).
infection (continued). "Moreover, GBP2 was found to be upregulated when reinfection was compared to primary infection for Chlamydia pneumoniae." (PMID 41181145, 2025). "GBP2 plays a specific and non-redundant role in controlling T. gondii, and its deficiency in mice increases susceptibility to infection." (PMID 41181145, 2025). "Interestingly, Gbp2 and Gbp9 were also elevated following infection with both L. mexicana and L. amazonensis, while Gbp5 trended towards an increase following infection with both species similar to L. major infection." (PMID 40631203, 2025). "Gbp2 and Gbp5 were among the top upregulated ISGs in IECs during infection." (PMID 40885187, 2025). "Consequently, we investigated the impacts of GBP2 on the infection by MLVs exhibiting different strains in this study." (PMID 39337476, 2024). "Besides GBP5, we also studied GBP2, due to its high expression profile and its aggregation near BCVs during infection." (PMID 38404575, 2024). "Besides, the presence of elevated levels of viral replication was observed as early as 4 h after infection, indicating that GBP2 plays a vital role in restricting the growth of ECTV." (PMID 37764102, 2023). "Additionally, Western blotting analysis confirmed a significant decrease in GBP2 expression in the sh-GBP2 cells following ECTV infection." (PMID 37958732, 2023). "Analysis of the vessel data revealed several proteins related to the acute-phase response to infection (Hp, Hpx, Serpina3n, Fga/b, Igfbp7, Cfh, and C4b), antigen presentation (Tap1, Tap2, Tapbp, H2-D1, and H2-Q10), and interferon response (Igtp, Gbp2, Irgm1, and Iigp1)." (PMID 32843537, 2020). "Similarly, in agreement with our analysis of PAMP-triggered expression, we found that Gbp2 mRNA expression was higher in C57BL/6J compared to 129/Sv mice following infection with either type II (Pru) or type I (RH)Toxoplasma." (PMID 31544161, 2019). "Notably, GBP2 efficiently decorates C. trachomatis inclusions, but is absent from C. muridarum inclusions in both murine embryonic fibroblasts and macrophages at various time points post-infection." (PMID 41181145, 2025). "To validate this up-regulation, we quantified the expression of IL6, GBP1, GBP2 and ISG15 in the same infection condition as bulk RNA-seq by qPCR." (PMID 39777915, 2025). "Numerous host proteins were upregulated upon infection with Francisella, ranging from immune-related proteins to metabolic enzymes, including notably IRG1, MARCO, Rilpl2, C3, PcgF5, MT1, TRAF1, GBP2 and Fas." (PMID 38565565, 2024). "In this regard, C57BL/6 wild-type, GBP2-/-, GBP5-/- and GBPchr3-/- mice were infected with B. abortus and monitored for two weeks post-infection." (PMID 38404575, 2024). "When overexpression of GBP2 was utilized to investigate its impact on ECTV, it predominantly exhibited its influence during the later phase of infection." (PMID 37764102, 2023). "Infection of bone marrow–derived macrophages from BALB/c mice with Leishmania major promastigotes led to up-regulation of expression of Gbp2b/Gbp1, Gbp2, Gbp3, Gbp6, and Gbp7 mRNA." (PMID 35085246, 2022). "The gene expression of GBP2 is more than 10-fold increased at the 7 and 10 days after SIV infection when compared with that before infection." (PMID 27280726, 2016). "Hence, the increased susceptibility in Gbp1−/− or Gbp2−/− mice to chronic infection may reflect reduced NO production locally within the CNS, or result from impaired clearance via the IRG or GBP pathways, leading to higher chronic burdens of infection." (PMID 23633952, 2013). "As early as 2 hours post-infection, we observed significantly increased GBP2, GBP5 and GBP7 mRNA levels compared to non-infected cells." (PMID 38404575, 2024). "229E infection did not induce GBP2, but significantly increased the expression of all other genes at 4 days after infection." (PMID 37197656, 2023).
infection (continued). "While GBP2 induction in MRC5 cells infected with 229E or OC43 infection was lower than those stimulated with IFN-γ, the expression levels of RIG-I and STAT2 induced by 229E or OC43 infection were similar to those induced by IFN-α or -γ stimulation." (PMID 37197656, 2023). "Infection of mouse embryonic fibroblasts (MEFs) and peritoneal exudate cells (PECs) derived from the strain C57BL/6 with Leishmania donovani led to increase of Gbp2 mRNA and GBP2 protein." (PMID 35085246, 2022). "Importantly, we found that WT, Gbp1–/–, Gbp2–/–, Gbp3–/–, Gbp5–/–, and Aim2–/– BMDMs all released similar levels of IL-1β, IL-18 and LDH in response to infection with F. novicida in the presence of E. coli LPS." (PMID 35906252, 2022). "To investigate whether individual GBPs are responsible for IRGB10 recruitment, we overexpressed IRGB10 and one GBP at a time (GBP1, GBP2, GBP3, GBP5 or GBP7) in LA-4 cells followed by infection with F. novicida." (PMID 35906252, 2022). "Finally, heightened induction of Gbp2, Gbp4, Gbp5, Gbp6, and Ip10 in Sts−/− cells relative to wild type cells was observed following both IFNγ treatment alone and LVS infection of IFNγ‐treated cells." (PMID 32841534, 2020). "Mice lacking GBP2, GBP5, or multiple GBPs on chromosome 3 (GBP2, GBP2b (GBP1), GBP3, GBP5, GBP7) were significantly more susceptible to infection, revealing a critical role for these proteins in restricting bacterial infection." (PMID 32150572, 2020). "After 24 h of infection, we observed that fibroblasts overexpressing GBP2 but not empty vector, GBP2ΔCAAX, or GBP2K51A were able to restrict bacteria-induced fusion." (PMID 32150572, 2020). "Expression of Gbp5 was strongly induced upon infection with T. gondii, while Gbp2 and Gbp7 were induced at lower levels, and no substantial change was seen in Gbp1 or Irga6." (PMID 30154263, 2018). "It is possible that GBP2 is not required for inflammasome responses to L. pneumophila or that siRNA-mediated knockdown in primary hMDMs was not efficient enough to reveal a role for GBP2 during infection." (PMID 37737612, 2023). "Furthermore, we observed that infection with either virus did not induce the upregulation of GBP2 expression in the sh-GBP2 cells, providing additional evidence of the effectiveness of knockdown." (PMID 37958732, 2023). "In view of the important role of GBP for the control of the LVS and F. novicida infections, but not the SCHU S4 infection, it was investigated whether expression of GBP2 and GBP5 was differentially affected at the gene or protein levels by the infections." (PMID 35004352, 2021). "It is conceivable that global Gbp1 and Gbp2 ubiquitination status might not change during infection, while this modification might target the defence proteins specifically to Toxoplasma PVs to excert their function." (PMID 29510761, 2018). "Interestingly, neither GBP2 nor IRGB10 is involved in >regulating inflammasome activation during infection with wild type Pseudomonas." (PMID 30062052, 2018). "Specifically, we found that following IFN-γ treatment, GBPs are expressed throughout the cell and upon infection with L. major, GBP localization does not change and GBP2 does not migrate to L. major." (PMID 40631203, 2025). "Regardless of these transcriptional differences, the IFN-γ-induced expression of GBP2 and GBP5 was not affected by the infections." (PMID 35004352, 2021). "Consistent with the microarray, protein levels of GBP2 and GBP5 were reduced in the Ifnar1−/−, Irf9−/−, Irf1−/−, Trif−/−, and Irf3−/−Irf7−/− macrophages that undergo extensive cell-cell fusion during infection but not in Myd88−/−." (PMID 32150572, 2020). "flexneri infection in 129/Sv, but not C57BL6/J mice, while Gbp2 expression was generally higher in C57BL6/J compared to 129/Sv mice." (PMID 31544161, 2019). "Similar to infection with S. flexneri, expression of WT, but not catalytically inactive IpaH9.8, drastically reduced levels of GBP1, GBP2, and GBP4, but not GBP3." (PMID 29024643, 2017).
infection (continued). "Whether CTB- or electroporation-mediated LPS transfer physiologically happens or not is uncertain, however, infection of Vibrio cholerae, which naturally possesses CTB, might activate caspase-11 inflammasome in GBP2-dependent and -independent pathways." (PMID 33042141, 2020).
tumor (49 papers, 2014 to 2026). "For instance, ZFP36 downregulation has been linked to worse survival, while GBP2 expression appears to contribute to immune activation and tumor suppression." (PMID 41154810, 2025). "Experiments in tumor-bearing mice further confirmed that GBP2 loss abrogated the efficacy of PD-1 blockade." (PMID 35383115, 2022). "Univariate Cox analysis suggested that the expression of GBP2 and several clinical parameters, including age, tumor stage, node stage, and histologic grade, were associated with poor OS in PAAD patients." (PMID 34026364, 2021). "Furthermore, GBP2 expression shows significant association with the mitogen-activated protein kinase and Wnt signaling pathways, both known to promote tumor occurrence and malignancy in various cancers." (PMID 41181145, 2025). "GBP2 was upregulated in tumor tissues but associated with well prognosis." (PMID 37784054, 2023). "Furthermore, anti-PD-1 treatment resulted in a tumor inhibition rate of about 43.7%, whereas depletion of GBP2 only caused about 16.9% tumor inhibition rate, indicating a potential role of GBP2 in the responsiveness to PD-1 blockade." (PMID 35383115, 2022). "Multiple pathways showed that GBP2 was associated with tumor immunity." (PMID 36186425, 2022). "GBP2, an interferon-inducible GTPase, indicates type I/II IFN activity and has been associated with antigen processing and inflamed tumor phenotypes." (PMID 41601673, 2026). "GBP2 is expressed at variable levels across diverse human malignancies and exhibits context-dependent roles in tumor progression." (PMID 41181145, 2025). "While most studies on GBP2 have focused on its role in oncology, particularly in promoting tumor proliferation and invasion, recent research has uncovered its significant immunoregulatory functions." (PMID 40156957, 2025). "GBP2 plays context-dependent roles in tumor progression, with evidence supporting both promotive and inhibitory functions across different cancer types." (PMID 41181145, 2025). "In pancreatic cancer, GBP2 acts as an acidosis-related signature, enabling tumor cells to thrive in hypoxic, acidic microenvironments, thus exacerbating disease progression by enhancing cell survival and metastasis." (PMID 40564939, 2025). "Numerous studies have highlighted GBP2’s dual role in cancer biology, with some defining it as a tumor suppressor across various cancer types, while others characterize it as an oncogene." (PMID 41181145, 2025). "This anti-tumor effect involves GBP2’s homodimerization and GTPase activity, which suppress PI3K/AKT/mTOR signaling, reducing cell proliferation and sensitizing tumors to paclitaxel." (PMID 40564939, 2025). "Using multi‐omics sequencing alongside various tumor‐bearing mouse models, we found that nanovaccines promote the M1 polarization of macrophages via the Gbp2‐Pin1‐NF‐κB signaling cascade, thereby achieving antitumor effects." (PMID 39985265, 2025). "In PAAD, GBP2 has been shown to directly interact with cyclin proteins such as p27, promoting tumor cell proliferation by regulating the G2/M transition." (PMID 41595468, 2025). "In melanoma, GBP2 is shown to be a favorable prognostic marker, and its overexpression can reduce tumor malignancy by inhibiting the Wnt/β-catenin pathway." (PMID 40564939, 2025). "Beyond infectious disease, GBP2 demonstrates a context-dependent dual role in cancer—acting as either a tumor suppressor or an oncogene by modulating key signaling pathways including JAK-STAT, Wnt/β-catenin, and PI3K/AKT/mTOR." (PMID 41181145, 2025). "At a molecular level, gene expression–based risk models (e.g., GBP2, PLEKHO2, MPP1, VSIG4) have been shown to have prognostic significance, but high tumor purity correlates with more aggressive disease." (PMID 41154810, 2025). "The risk model incorporated immune-related genes such as GBP2, SEMA4D, and KIR2DL4, which demonstrated distinct tumor expression profiles and strong prognostic value." (PMID 40319421, 2025).
tumor (continued). "For example, GBP2 activated caspase-4, that triggered cell death and inhibited tumor cell proliferation, and SLC40A1, that acted as a negative regulator of ferroptosis." (PMID 36899891, 2023). "Together, the information points to GBP2 as an immunotherapy pan-cancer biomarker, with the exception of a few tumor types." (PMID 37784054, 2023). "Through the regulation of the tumor immune microenvironment, GBP2 can influence the prognosis of various malignancies." (PMID 37370817, 2023). "The pan-cancer study also shows that GBP2 is a marker for high immunogenicity in the majority of tumor types." (PMID 37784054, 2023). "In the GEPIA database, GBP2 was significantly upregulated in tumor tissues compared with para-tumor tissues." (PMID 37784054, 2023). "It has been shown in several studies that GBP2 models the immune microenvironment of the tumor and that its degree of expression is correlated with the rate of immune infiltration." (PMID 37370817, 2023). "The results showed that GBP2 protein was located in cytoplasm and highly expressed in tumor tissues." (PMID 37784054, 2023). "GBP2 dramatically promotes GBM tumor growth and invasion in mice and significantly reduces the survival time of the mice with a tumor." (PMID 36980765, 2023). "We analyzed the change of GBP2 among 33 cancer types by comparing tumor tissue with normal tissue and adjacent normal tissue." (PMID 36186425, 2022). "Among the published reports, GBP2 has been shown to be a mediator of tumor and intracellular immunity." (PMID 36091803, 2022). "Nevertheless, in wild-type mice, the tumor volume of GBP2 KO +IgG group was significantly larger than that for Vec+IgG group." (PMID 35383115, 2022). "The results showed that the expressions of GBP1 and GBP2 in normal tissues were significantly higher than those in tumor tissues." (PMID 36246628, 2022). "Increased GBP2 expression in BC showed correlations with improved survival and tumor-infiltrating T cell." (PMID 35233733, 2022). "The protein expression of GBP2 was higher in the tumor tissues compared to the normal tissue, which was consistent with our results from RT-qPCR." (PMID 35356208, 2022). "We found that only a slight increase in tumor volume was observed in GBP2 KO tumors implanted in immunodeficient NSG mice." (PMID 35383115, 2022). "The GBP2-related signaling pathway mainly correlated with tumorigenesis, invasion, and the immune microenvironment of tumor cells." (PMID 34026364, 2021). "The relationship between GBP2 and tumor immunity was evaluated to elucidate the role of GBP2 in the PAAD tumor environment." (PMID 34026364, 2021). "CIBERSORT and the relative expression of immune checkpoints were used to estimate the relationship between GBP2 expression and tumor immunology." (PMID 34026364, 2021). "Here, weinvestigated GBP2 promoter methylation status in tumor and normalbreast tissues as well as tracing its pattern in plasma sample counterparts." (PMID 33211060, 2020). "Therefore, GBP1 and GBP2 may be also tumor suppressor genes and associated with better prognosis." (PMID 27806724, 2016). "Overexpression of NETO2, VCAN, and GBP2 in tumor tissues compared to normal tissues were observed in 93.75% (15/16), 93.75 (15/16), and 87.5% (14/16), respectively." (PMID 24783204, 2014). "The PLGA-CpG@ID8-M nanovaccine overcomes free CpG accumulation, reprograms TAMs to tumoricidal M1 macrophages via Gbp2/Pin1–NFκB signaling, inhibits tumor growth, and counteracts chemotherapy-induced immunosuppression by boosting M1 TAMs and lowering tumor CD47." (PMID 41280929, 2025). "GBP2, a GTPase family member, and SLA are implicated in immune regulation and tumor growth." (PMID 41438620, 2025). "GBP2 contributes to tumor regulation by modulating apoptotic pathways." (PMID 41181145, 2025). "LY6D and GBP2 are primarily involved in regulating immune cells and advancing the tumor cell cycle." (PMID 41595468, 2025).